PDK4 (pyruvate dehydrogenase kinase 4)
Diseases named in the same sentence as PDK4 in open-access papers (continued):
Sharing a sentence is not in itself a finding about the gene and the disease.
endometrial cancer (2 papers, 2012 to 2020). Primary or metastatic malignant neoplasm involving the endometrium (mucous membrane that lines the endometrial cavity). "The specific role that PDK4 plays in endometrial cancer remains to be deciphered." (PMID 22911820, 2012). "We have demonstrated a cooperation of PR and FOXO1 in regulating genes in endometrial stromal cells and thus it is likely that PDK4 upregulation by progestins requires both PR and FOXO1 in endometrial cancer cells." (PMID 22911820, 2012).
epilepsy (2 papers, 2025). A brain disorder characterized by episodes of abnormally increased neuronal discharge resulting in transient episodes of sensory or motor neurological dysfunction, or psychic dysfunction. "Although there is relatively limited research regarding its connection with epilepsy, it is recommended to verify further the roles of GPT2 and miR-212-39/PDK4 in TLE." (PMID 40242460, 2025).
Hypoglycemia (2 papers, 2016 to 2017). A decreased concentration of glucose in the blood. "Both C/EBPβ–/–mice and PDK4–/–mice display hypoglycemia and increased insulin sensitivity." (PMID 27711113, 2016).
intestinal cancer (2 papers, 2021 to 2022). "Moreover, high expression of PDK4 has been found to accelerate the growth of cancer cells and promote metastasis, such as in bladder, breast, and intestinal cancer." (PMID 36358433, 2022).
kidney damage (2 papers, 2023 to 2026). "Recently, mitochondrial pyruvate dehydrogenase kinase 4 (PDK4) expression was shown to be induced by IRI and genetic and pharmacological PDK4 inhibition before IR, reducing succinate accumulation and kidney damage." (PMID 37894994, 2023). "Further analysis revealed that while RHCG exhibited distinct expression patterns in DKD compared to other nephropathies, FBP1 and PDK4 showed comparable expression levels across disease types." (PMID 41481634, 2026).
left ventricular hypertrophy (2 papers, 2011 to 2025). Enlargement of the LEFT VENTRICLE of the heart. "Notably, a previously published omics study in cardiac tissue from patients with left ventricular hypertrophy similarly reported significantly higher PDK4 expression in men than in women, highlighting the clinical relevance for sex-biased PDK4 regulation." (PMID 40626362, 2025).
liver disease (2 papers, 2023 to 2024). "Here the authors report that PDK4 promotes Ca2 + -channelling complex formation at the endoplasmic reticulum-mitochondria contact sites, which contributes to the pathogenesis of alcohol-associated liver disease in studies with male mouse and hepatocyte models." (PMID 36973273, 2023). "A recent study using a mouse model of alcohol-associated liver disease revealed that alcohol increased the numbers of MAMs, resulting in mitochondrial dysfunction, in a pattern dependent upon the MAM-associated pyruvate dehydrogenase kinase 4 (Pdk4/PDK4)." (PMID 38540197, 2024).
liver fibrosis (2 papers, 2015 to 2024). "An increase in Pdk4 expression has been reported in two independent mouse models of liver fibrosis, resulting from chemical-induced liver damage and chronic biliary injury." (PMID 26047317, 2015).
metastatic tumors (2 papers, 2020 to 2022). "Expression analysis of PDK4 in human PC reveals an inverse correlation with miR-32 expression and Gleason score, a decrease in castration-resistant and metastatic tumors compared to untreated primary PC, and an association of low PDK4 expression with a shorter recurrence-free survival of patients." (PMID 35228520, 2022). "In addition, PDK4 is an independent predictor of BCR compared to ISUP grading and clinical staging, as well as pathological staging and pre‐surgical PSA levels in primary and metastatic tumors, identifying PDK4 as a promising prognostic marker in PCa." (PMID 32323921, 2020). "PDK4 was a significant predictor of BCR both in primary tumors (univariate Cox PH model: beta: −0.758, HR: 0.469, P‐value: 0.001) and in primary and metastatic tumors combined (beta: −0.981, HR: 0.375, adj P‐value: 2.25e‐05, Table EV5)." (PMID 32323921, 2020). "In addition, PDK4 is an independent predictor of biochemical recurrence compared to ISUP grading and clinical staging, as well as pathological staging and pre‐surgical PSA levels in primary and metastatic tumors." (PMID 35228520, 2022). "In addition, PDK4 was a significant predictor independent of ISUP grading and clinical tumor staging as well as pathological tumor staging and pre‐surgical PSA levels in primary and metastatic tumors combined." (PMID 32323921, 2020).
myocardial infarction (2 papers, 2021 to 2025). Gross necrosis of the myocardium, as a result of interruption of the blood supply to the area, as in coronary thrombosis. "Moreover, pyruvate dehydrogenase kinase 4 (PDK4) knockout mice which have reduced fatty acid utilization showed increased cardiomyocyte proliferation after myocardial infarction." (PMID 40338840, 2025).
neuroblastoma (2 papers, 2021 to 2025). Neuroblastoma (NB) is the most common solid, extracranial childhood tumor. "The diminution of Pdk4 observed in hAPP-expressing cells indicates that hAPP expression and/or increase in total APP content enhances glycolytic metabolism, as reported in human neuroblastoma cells in which increase in neuronal hAPP levels mediates an Aβ-independent Pdk4 downregulation." (PMID 34228639, 2021). "GRP-R regulates glucose metabolism in neuroblastoma by modulating HIF-1α, PDK4, and PDP2." (PMID 40746885, 2025).
non-alcoholic steatohepatitis (2 papers, 2018 to 2022). "Independent studies revealed PDK4 activity to be influenced by thiazolidinediones and pioglitazone was shown to improve liver histology and fibrosis in patients with non-alcoholic steatohepatitis." (PMID 30547786, 2018).
osteoporosis (2 papers, 2012 to 2022). A condition of reduced bone mass, with decreased cortical thickness and a decrease in the number and size of the trabeculae of cancellous bone (but normal chemical composition), resulting in increased fracture incidence. "Our BCL2 transgenic mice was also a useful tool to search the molecular targets of disuse osteoporosis, because we found that Pdk4 is responsible for bone loss at unloading by comparing the genes induced in wild-type mice and BCL2 transgenic mice at 4 months of age in the unloaded condition." (PMID 22768243, 2012).
prion disease (2 papers, 2021 to 2025). A transmissible disease that is caused by a protein that is able to induce abnormal folding of normal cellular proteins, leading to characteristic spongiform brain changes, which are associated with neuronal loss without an inflammatory response. "Next, the status of PDK4 level was analyzed in an already characterized prion disease model of neurodegeneration." (PMID 40730554, 2025). "The inhibition of PDK4 extends the survival of prion-infected mice, supporting that PrPSc-induced deregulation of PDK4 activity and subsequent metabolic derangements contribute to prion diseases." (PMID 34610054, 2021). "This posits PDK4 as a potential therapeutic target to fight prion diseases and possibly other amyloid-based neurodegenerative diseases by rescuing a normal glucose oxidative flux and limiting the use of fatty acids." (PMID 34610054, 2021). "This argues that PrPSc-induced deregulation of PDK4 activity and the subsequent metabolic abnormalities contribute to neurodegeneration in prion diseases." (PMID 34610054, 2021). "Of note, pharmacological inhibition of PDK4 in mice was performed at a late stage of prion disease, i." (PMID 34610054, 2021). "Altogether, these data support a new role of PrPC in the control of the cell energetic metabolism and the cell redox status, whose deregulation by pathogenic prions contributes to neurodegeneration, and introduce PDK4 as a potential therapeutic target to fight against prion diseases." (PMID 34610054, 2021). "Our study posits PDK4 as a potential therapeutic target to fight against prion diseases." (PMID 34610054, 2021).
prostate tumor (2 papers, 2022 to 2023). "A similar inverse correlation between miR-32 and PDK4 expression was observed in an independent, publicly available data set of primary prostate tumor samples." (PMID 35228520, 2022). "Collectively, our results show that PDK4 affects PC cell metabolism and provide a mechanistic explanation of the benefit of PDK4 downregulation in advanced prostate tumors." (PMID 35228520, 2022). "PDK4 expression was also lower in primary prostate tumors of higher Gleason grade (>7), and low PDK4 expression in primary tumors was associated with a shorter recurrence-free survival of patients." (PMID 35228520, 2022). "Of the two other genes indicated as direct, downregulated targets for miR-32, namely Pck1 and Pdk4, Pck1 is not expressed in prostate tumors of patients (data not shown) and thus it is also unlikely to represent a clinically relevant miR-32 target in PC." (PMID 35228520, 2022).
thyroid cancer (2 papers, 2023). "As reported, circCCDC66 promotes thyroid cancer cell proliferation, migratory and invasive abilities, and glycolysis through the miR-211-5p/PDK4 axis." (PMID 38098508, 2023). "In addition, circCCDC66 in thyroid cancer acts as a sponge for miR-211-5p, which enhances the expression of PDK4 protein, promotes the proliferation, migration, and invasion of thyroid cancer." (PMID 37599427, 2023).
adrenocortical carcinoma (1 paper, 2024). "Specifically, PDK4 was found to act as a protective factor in liver hepatocellular carcinoma (LIHC), kidney renal clear cell carcinoma (KIRC), low-grade glioma, and skin cutaneous melanoma, while acting as a risk factor in adrenocortical carcinoma and stomach adenocarcinoma (STAD)." (PMID 38914792, 2024).
alcoholic liver diseases (1 paper, 2026). A disorder caused by damage to the liver parenchyma due to alcohol consumption. "Previous studies have reported that in alcoholic liver disease, PDK4 phosphorylation of its downstream target GRP75 promotes MCC complex formation, leading to mitochondrial calcium accumulation and dysfunction." (PMID 41355952, 2026).
Anorexia (1 paper, 2020). Lack of desire to eat (loss of appetite). "Glucose administration likely stimulated the insulin receptor-AKT signaling pathway to decrease FOXO1 activation to blunt the increase in PDK4 levels resulting from anorexia to maintain energy generation." (PMID 33014275, 2020). "However, the infection led to severe anorexia, which also increases PDK4 levels in some tissues such as those in the muscle and liver due to increased FOXO1, PPAR-α, and glucocorticoid receptor (GR) transcriptional activity." (PMID 33014275, 2020).
benign prostatic hyperplasia (1 paper, 2023). A non-cancerous nodular enlargement of the prostate gland. "The results showed that overexpression of PDK4 in the prostatic hyperplasia cell line could suppress the progression of BPH, manifested as a lower level of proliferation, higher level of apoptosis, and limited EMT." (PMID 37863991, 2023).
depression (1 paper, 2020). "Moreover, in addition to a reduction in pyruvate dehydrogenase levels, a decrease in pyruvate dehydrogenase kinase 4, the enzyme that inhibits pyruvate dehydrogenase, was observed only in the model of depression with hypothyroidism." (PMID 33343282, 2020).
endotoxemia (1 paper, 2025). "Here, we used a mouse model of endotoxemia and found that acute inflammation significantly increased PDK4 expression in male compared with female hearts, with PDK4 expression being associated with sex-specific cardiac performance." (PMID 40626362, 2025). "The present study was designed to investigate the role of PDK4 in cardiac outcomes following endotoxemia." (PMID 40626362, 2025). "Conversely, PDK4 knockout protected cardiac mitochondria and reduced oxidative stress in both sexes during endotoxemia." (PMID 40626362, 2025). "Taken together, these results suggest that PDK4 upregulation promoted cardiac dysfunction by impairing mitochondrial health and increasing oxidative damage in the myocardium during endotoxemia." (PMID 40626362, 2025). "Together, these results show that PDK4 upregulation disrupts mitochondrial structure and has additional regulatory roles in mitochondrial dynamics in the heart during endotoxemia." (PMID 40626362, 2025). "PDK4 upregulation impairs mitochondria health and induces oxidative stress during endotoxemia." (PMID 40626362, 2025). "PDK4 drives sex-based differences in cardiac metabolism during endotoxemia." (PMID 40626362, 2025). "Taken together, these findings suggest that PDK4 may play a previously unrecognized role in mediating sex-specific cardiac performance in response to the acute inflammatory challenge induced by endotoxemia." (PMID 40626362, 2025). "In females, PDK4 overexpression primarily increased IL-6 expression and significantly elevated MPO levels during endotoxemia compared with WT females." (PMID 40626362, 2025). "Taken together, these findings suggest that DCA-mediated protection against endotoxemia-induced cardiac dysfunction is sex specific, and they further imply that, in females, cardiac dysfunction may involve mechanisms beyond impaired glucose metabolism regulated by PDK4–PDH signaling axis." (PMID 40626362, 2025). "In a mouse endotoxemia model, a sublethal dose of lipopolysaccharide (LPS, 5 mg/kg) significantly upregulated myocardial PDK4 and induced cardiac dysfunction in males but not females." (PMID 40626362, 2025).
Gerstmann-Sträussler-Scheinker syndrome (1 paper, 2025). "Our results showed that PDK4 was upregulated in the presence of the natural Gerstmann-Sträussler-Scheinker syndrome (GSS) variant of PrP (A117V) that is known to generate CtmPrP in abundance and ER stress." (PMID 40730554, 2025).
hyperandrogenism (1 paper, 2024). Excessive secretion of androgens from the adrenal glands or gonads. "Through RNA-seq analysis, we found that PDK4 expression was significantly downregulated in the endometrium of PCOS women with hyperandrogenism, while other members of the PDK family displayed no significant changes." (PMID 39080028, 2024). "In particular, the hierarchical cluster analysis revealed that PDK4, which is involved in the glycolysis process, exhibited a significantly lower expression in PCOS women with hyperandrogenism." (PMID 39080028, 2024). "In particular, the expression levels of PDK4, a representative enzyme that regulates the glycolysis process, was significantly decreased in the hyperandrogenism group compared with PCOS patients without hyperandrogenism." (PMID 39080028, 2024). "RNA-Seq analysis demonstrated that pyruvate dehydrogenase kinase 4 (PDK4) expression was significantly lower in the endometrium of PCOS patients with hyperandrogenism compared to those without hyperandrogenism." (PMID 39080028, 2024). "The present study further demonstrated that glycolysis-related gene, especially PDK4, has a lower expression in PCOS with hyperandrogenism compared with PCOS without hyperandrogenism." (PMID 39080028, 2024).
Hyperinsulinemia (1 paper, 2018). An increased concentration of insulin in the blood. "Knockdown of HPS90ab1 in DIO mice improved glucose tolerance, hyperinsulinemia, and was associated with significant lowering of PDK4 expression." (PMID 29434648, 2018).
idiopathic pulmonary arterial hypertension (1 paper, 2024). A sporadic form of pulmonary arterial hypertension (PAH) characterized by elevated pulmonary arterial resistance leading to right heart failure. "However, some studies have suggested a close association of PDK4 with idiopathic pulmonary fibrosis and idiopathic pulmonary arterial hypertension." (PMID 38672101, 2024).
Infertility (1 paper, 2024). "Overall, these findings indicate that dysregulation of PDK4 in the endometrium is a novel contributor to infertility in PCOS." (PMID 39080028, 2024). "Targeting PDK4 may hold promise as a potential therapeutic strategy for addressing infertility in PCOS patients." (PMID 39080028, 2024).
ischemic stroke (1 paper, 2023). A stroke disorder caused by obstruction of blood flow to the brain, due to thrombotic (local blood clot formation) or embolic (due to a blood clot or other material traveling from another site) event. "In mice with ischemic stroke, it was found that the cecum metabolism was disordered, and the PDK4 related to fatty acid metabolism was up-regulated, which may lead to the reduction of steroid metabolic process activity." (PMID 37795292, 2023).
kidney (1 paper, 2024). "We demonstrate that 4-PBA mitigates cisplatin-induced acute kidney injury by downregulating Pdk4, thereby preventing mitochondrial dysfunction and apoptosis in renal cells." (PMID 39767721, 2024).
lentivirus infection (1 paper, 2020). Virus diseases caused by the Lentivirus genus. "To determine the functions of PDK4 in GC cellular metabolism, we knockdown PDK4 expression in SGC7901 cells and upregulated its expression in BGC823 cells by lentivirus infection." (PMID 32780563, 2020).
leukaemia (1 paper, 2021). "The top 10 upregulated genes such as FEZ1 and PDK4 are reported with proto‐leukaemia effects." (PMID 34432355, 2021).
lung adenoma (1 paper, 2014). A benign, well circumscribed epithelial neoplasm that arises from the bronchus or the lung parenchyma. "Finally, analysis of human lung adenoma tumor samples reveals PDK4-low as a predictor of poor prognosis, consistent with PDK4’s role in EMT." (PMID 25379179, 2014).
lung disorder (1 paper, 2024). A disease involving the lung. "Previous studies have demonstrated the increased expression of PDK4 in the heart, pancreatic islets and skeletal muscles; however, its effect on lung disorders is not clear." (PMID 38672101, 2024).
membranous nephropathy (1 paper, 2026). "Notably, bioinformatics analyses and experimental evidence consistently demonstrate downregulated PDK4 expression in both membranous nephropathy patients and animal models, a phenomenon similarly observed in DKD." (PMID 41481634, 2026).
Mitochondrial myopathy (1 paper, 2025). "As our single nuclear RNASeq indicated decrease of Pdk4 transcript in oxidative type‐II fibers, where it typically is expressed, a possibility remains that another kinase phosphorylates PDH in large muscles in mitochondrial myopathy." (PMID 40681476, 2025).
myocarditis (1 paper, 2022). Myocarditis is a condition that is characterized by inflammation of the heart muscle (myocardium). "Here, investigation of the peripheral immune landscape of the patient in chronological order revealed that most differentially expressed genes are metabolic enzymes, including PDK4, the most upregulated gene in myocarditis, and genes involved in fatty acid metabolism." (PMID 36225942, 2022). "Also, we confirmed not only PDK4, but also CPT1A and ACSL1, which are known to be key regulators of fatty acid metabolism, are the target transcripts of CEBPB in classical monocytes in BNT162b2-myocarditis." (PMID 36225942, 2022).
nonalcoholic fatty liver (1 paper, 2022). "PDK4 expression is elevated in human NASH liver specimens, and deletion of PDK4 can alleviate nonalcoholic fatty liver in mice." (PMID 35251469, 2022).
oral cancer (1 paper, 2022). "The expression levels of FABP3, PPARG, PLIN5, ACACB, and PDK4 in oral cancer samples were significantly lower than those in adjacent normal samples (all p < 0.05) and then were included in the prognosis analysis." (PMID 36478991, 2022).
ovarian dysfunction (1 paper, 2018). The inability of the ovaries to function. "Our findings provide the rationale for PDK4 as a key and potential therapeutic target to ameliorate and preserve the competence of oocytes, and support the application of putrescine to slow the oxidative stress-mediated aging of oocytes and ovarian dysfunction." (PMID 30554191, 2018).